ENSG00000285629 (novel transcript)
Gene: Protein-coding gene on chromosome 1 (6,159,430 to 6,197,757, reverse strand). Ensembl gene ENSG00000285629.
Genetic constraint (gnomAD): Missense variants: 29 observed, 55.91 expected, observed/expected ratio (o/e) 0.52, 90% interval 0.38 to 0.71. Synonymous variants: 16 observed, 21.65 expected, observed/expected ratio (o/e) 0.74, 90% interval 0.5 to 1.12.